MINK1 (misshapen like kinase 1)
Description:
Serine/threonine kinase which acts as a negative regulator of Ras-related Rap2-mediated signal transduction to control neuronal structure and AMPA receptor trafficking. Required for normal synaptic density, dendrite complexity, as well as surface AMPA receptor expression in hippocampal neurons (By similarity). Can activate the JNK and MAPK14/p38 pathways and mediates stimulation of the stress-activated protein kinase MAPK14/p38 MAPK downstream of the Raf/ERK pathway. Phosphorylates TANC1 upon stimulation by RAP2A, MBP and SMAD1. Has an essential function in negative selection of thymocytes, perhaps by coupling NCK1 to activation of JNK1 (By similarity). Activator of the Hippo signaling pathway which plays a pivotal role in organ size control and tumor suppression by restricting proliferation and promoting apoptosis. MAP4Ks act in parallel to and are partially redundant with STK3/MST2 and STK4/MST2 in the phosphorylation and activation of LATS1/2, and establish MAP4Ks as components of the expanded Hippo pathway. Isoform 4 can activate the JNK pathway. Involved in the regulation of actin cytoskeleton reorganization, cell-matrix adhesion, cell-cell adhesion and cell migration.
Synonyms: MEKKK 6; B55; MAP4K6; MINK; YSK2; ZC3
Tractability: Small molecule: a high-quality ligand is known; it belongs to a druggable protein family. PROTAC: it is named in the literature on targeted protein degradation; ubiquitination databases record sites on it; its protein half-life has been measured; a small molecule that binds it is known.
Target class: Kinase; STE protein kinase group; STE protein kinase STE20 family; STE protein kinase MSN subfamily; Protein Kinase; Enzyme
Gene: Protein-coding gene on chromosome 17 (4,833,147 to 4,898,065, forward strand). Ensembl gene ENSG00000141503.
Subcellular location: Cytoplasm; Postsynaptic density; Cell projection, axon; Cell projection, dendrite; Golgi apparatus (Isoform 4)
Pathways (Reactome):
Cellular responses to stimuli: Oxidative Stress Induced Senescence
Gene Ontology:
Molecular function: protein binding; protein serine/threonine kinase activity; ATP binding; protein kinase activity; protein serine kinase activity
Biological process: actin cytoskeleton organization; positive regulation of JNK cascade; protein autophosphorylation; protein phosphorylation; regulation of cell migration; regulation of cell-cell adhesion; regulation of cell-matrix adhesion; brain development; chemical synaptic transmission; dendrite morphogenesis; JNK cascade; MAPK cascade; neuron projection morphogenesis; positive regulation of p38MAPK cascade; regulation of AMPA receptor activity; regulation of MAPK cascade; positive regulation of intracellular signal transduction; regulation of JNK cascade
Cellular component: cytoplasm; extracellular exosome; Golgi apparatus; cytosol; axon; dendrite; postsynaptic density
Genetic constraint (gnomAD): Loss-of-function variants: 46 observed, 146.04 expected, observed/expected ratio (o/e) 0.31, 90% interval 0.25 to 0.4. The synonymous counts are far from expectation, so gnomAD's model fits this gene poorly and the ratio says little. Missense variants: 1,366 observed, 1,682.7 expected, observed/expected ratio (o/e) 0.81, 90% interval 0.78 to 0.85. Synonymous variants: 797 observed, 645.09 expected, observed/expected ratio (o/e) 1.24, 90% interval 1.16 to 1.31.
Homologues: Orthologues: macaque MINK1 (99% identical), chimpanzee MINK1 (97% identical), rat Mink1 (97% identical), mouse Mink1 (97% identical), guinea pig MINK1 (97% identical), dog MINK1 (96% identical), pig MINK1 (95% identical), rabbit MINK1 (94% identical), tropical clawed frog mink1 (76% identical), zebrafish mink1 (74% identical), Drosophila melanogaster msn (50% identical), Caenorhabditis elegans mig-15 (42% identical). Paralogues in human: TNIK (66% identical), MAP4K4 (65% identical), NRK (34% identical), MAP4K3 (19% identical), SLK (19% identical), MAP4K5 (17% identical), MAP4K2 (17% identical), STK10 (17% identical), TAOK1 (16% identical), MAP4K1 (16% identical), TAOK3 (15% identical), TAOK2 (15% identical), and 23 more.
Diseases named in the same sentence as MINK1 in open-access papers:
MINK1 is named in the same sentence as 45 diseases in open-access papers, as found by Europe PMC text mining. Sharing a sentence is not in itself a finding about the gene and the disease. The quoted sentences say what the papers report.
breast carcinoma (6 papers, 2022 to 2025). "An inverse correlation between MINK1 expression and miR-17-5p levels was observed across 1085 breast cancer specimens in the TCGA dataset." (PMID 39963142, 2025). "This indicates that CDKN1A and MINK1 are downregulated in breast cancer relative to normal tissue, while SQSTM1 shows upregulation in the same comparison." (PMID 39963142, 2025). "RES induces ULBP2 expression and consequently enhances breast cancer cell elimination by NK cells through the suppression of miR-17-5p and activation of the MINK1/JNK/c-Jun cascade." (PMID 39963142, 2025). "In this work, the activation of JNK and its downstream effector molecule c-Jun was attenuated in breast cancer cells overexpressing miR-17-5p or subjected to MINK1 knockdown, whereas miR-17-5p downregulation or MINK1 upregulation led to opposing outcomes." (PMID 39963142, 2025). "Depletion of either PRICKLE1 or MINK1 in breast cancer cells has been demonstrated to reduce cell motility by promoting the formation of dense actin bundles and cellular spreading." (PMID 39123414, 2024). "Higher MINK1 levels were found to be correlated with shorter overall survival of the patients (p = 0.011) suffering from breast cancer." (PMID 39727954, 2024). "For example, MINK1 knockdown results in decreased breast cancer cells’ ability to invade secondary organs in vivo in comparison to control cells." (PMID 39727954, 2024). "Earlier it was proven that selective knockdown of MINK1 decreases the migration of human breast cancer lines." (PMID 36182968, 2022). "In conclusion, MINK1 is likely involved in the metastatic spread of cancer cells in breast cancer." (PMID 39727954, 2024). "Several researchers examined the function of MINK1 in breast cancer." (PMID 39727954, 2024). "Detection of the expression level of MINK1 in human tissues could be a potentially useful prognostic marker in many pathological states, such as breast cancer, head and neck squamous cell carcinoma (HNSC), hepatocellular carcinoma (HCC), or Alzheimer’s disease." (PMID 39727954, 2024). "MINK1 silencing resulted in decreased motility and proliferation of breast cancer and CRC cells, as well as reduced viability of OSCC cells, it can thus be involved in the metastatic spread of cancer cells and its targeting may be a good treatment strategy for several types of cancer." (PMID 39727954, 2024). "In breast cancer cells, Pk1 interacts with Mink1 and RICTOR to engage Akt signaling-mediated reorganization of the actin cytoskeleton to promotes breast cancer cell migration." (PMID 35646914, 2022). "Selectively targeting either of MINK1, PRICKLE1 or RICTOR can significantly decrease the migration of cancer cell in breast carcinomas." (PMID 36182968, 2022).
glioma (3 papers, 2022 to 2025). A benign or malignant brain and spinal cord tumor that arises from glial cells (astrocytes, oligodendrocytes, ependymal cells). "Potential diagnostic biomarkers MINK1, PLEKHM3, BZW1, and RCF2 had mRNA expression that differed significantly between GBM and the other glioma subtypes (p-values < 0.001)." (PMID 35877430, 2022).
rheumatoid arthritis (3 papers, 2023 to 2024). A chronic, systemic autoimmune disorder characterized by inflammation in the synovial membranes and articular surfaces. "MINK1 has been implicated in conditions including rheumatoid arthritis, asthma, and SLE, and its activity regulates the immune responses on many levels." (PMID 39727954, 2024). "Another clinical condition in which the essential role may be played by MINK1 is rheumatoid arthritis (RA)." (PMID 39727954, 2024). "Other reports implicate MINK1 in rheumatoid arthritis, asthma, and SLE." (PMID 39727954, 2024). "The CeRNA network illustrated that lncRNA SNHG14 could simultaneously interact with hsa-miR-515-5p and hsa-miR-185-3p, lncRNA SNHG14 could participate in the production of proinflammatory cytokines in rheumatoid arthritis by regulating the MINK1/JNK pathway." (PMID 37313407, 2023). "Moreover, miR-17-5p seems to target MINK1, and SNHG14 counterplays this regulation in rheumatoid arthritis." (PMID 39727954, 2024).
Alzheimer disease (2 papers, 2022 to 2024). A progressive, neurodegenerative disease characterized by loss of function and death of nerve cells in several areas of the brain leading to loss of cognitive function such as memory and language. "The synaptic PRS model including MINK1 is the simplest model allowing for identifying patients at risk of Alzheimer’s disease before the occurrence of first symptoms." (PMID 39727954, 2024). "Broce and colleagues showed that various CV-associated risk factors were connected to an increase in the risk of AD, even for people with genetic predispositions for developing Alzheimer’s disease, proving the complex nature of the disease and the possible role of MINK1 in its development." (PMID 39727954, 2024). "Numerous phosphopeptides are altered in the brains of patients with Alzheimer’s disease, as revealed by analyses of postmortem human brain tissues, suggesting that kinases, including MINK1, may play a role in the pathogenesis of AD." (PMID 39727954, 2024). "It is hence possible that MINK1 takes part in the pathogenesis of various diseases, in which neuronal morphology is altered, and which include mental retardation, epilepsy, schizophrenia, and Alzheimer’s disease." (PMID 39727954, 2024). "The modulation of MINK1 activity could influence the course of neurodegenerative diseases, including Alzheimer’s disease." (PMID 39727954, 2024). "As mentioned, MINK1 takes part in synaptic morphology and neural degeneration, so it could be involved in the pathogenesis of Alzheimer’s disease (AD)." (PMID 39727954, 2024).
asthma (2 papers, 2022 to 2024). "In conclusion, the data from this study demonstrated that MBD2-mediated Th17 cell differentiation is associated with reduced MINK1 expression in Th17-dominant asthma." (PMID 36303542, 2022). "The expression of MBD2 in lung tissues and BECs from the Th17-dominant asthma group was significantly increased, while the corresponding expression of MINK1 was significantly impaired." (PMID 36303542, 2022). "Compared to the T2 asthma group, the expression of MBD2 protein and mRNA in lung tissues and BECs from the Th17-dominant asthma group was significantly increased, while the corresponding expression of MINK1 mRNA and protein was significantly impaired." (PMID 36303542, 2022). "The aim of this study was to investigate how MBD2 interacts with MINK1 to regulate Th17 cell differentiation in Th17-dominant asthma." (PMID 36303542, 2022). "Our findings have revealed new roles for MBD2 and MINK1 and provide new insights into epigenetic regulation of Th17-dominant asthma, which is dominated by neutrophils and Th17 cells." (PMID 36303542, 2022). "In this study, we found that MINK1 was significantly reduced in lung tissues and BECs in the Th17-dominant asthma groups compared to that in T2 asthma groups." (PMID 36303542, 2022). "Together, these data indicated that MBD2 induced Th17 cell differentiation by maintaining MINK1 silencing, thereby contributing to the development of Th17-dominant asthma." (PMID 36303542, 2022). "Interesting studies have been performed regarding the role of MINK1 in asthma." (PMID 39727954, 2024). "Inducing MINK1 expression in asthma or targeting the SNHG14/MINK1 axis in RA could be considered interesting directions for future research." (PMID 39727954, 2024). "In addition, these results indicated that Th17 cells are not directly downstream of MBD2, and MBD2 regulates Th17 cell differentiation through negative regulation of MINK1 expression, thus mediating the onset of Th17-dominant asthma." (PMID 36303542, 2022). "In this study, we aimed to determine the role of MBD2 and MINK1 in Th17-dominant asthma." (PMID 36303542, 2022). "Taken together, these data suggested that MBD2 might promote Th17 cell differentiation by inhibiting MINK1, thereby exacerbating the severity of asthma." (PMID 36303542, 2022). "Misshapen like kinase 1 (MINK1) is involved in the regulation of Th17 cell differentiation, but its effect on severe asthma remains unclear." (PMID 36303542, 2022). "Therefore, we hypothesized that MINK1 is involved in asthma by regulating Th17 cell differentiation and may be a therapeutic target for Th17-dominant asthma." (PMID 36303542, 2022). "Consistently, the mRNA levels of MBD2 were elevated, while the levels of MINK1 mRNA were lowered, which suggests the involvement of MINK1 and MBD2 in the development of asthma phenotype and severity." (PMID 39727954, 2024). "Histological analyses revealed a marked decrease in MINK1 staining and increased methyl-CpG-binding domain protein 2 (MBD2) staining in the lungs of the mice in the Th17-asthma group." (PMID 39727954, 2024). "Th17-dominant asthma is mainly mediated by Th17 cells, and both MBD2 and MINK1 genes can affect the differentiation of Th17 cells." (PMID 36303542, 2022). "We induced Th17-dominant asthma mouse and BECs models and found that MBD2 was significantly increased in vivo and in vitro, while MINK1 was decreased, and there was a reverse expression between MBD2 and MINK1." (PMID 36303542, 2022). "In the present study, the results showed that compared to the asthma group, the histological analyses of lungs in the Th17-dominant asthma group showed significantly increased MBD2 staining and significantly decreased MINK1 staining." (PMID 36303542, 2022). "Moreover, exposure to HDM and LPS enhances MBD2 binding to the promoter region of the MINK1 gene, showing that MBD2 is the factor silencing MINK1 in Th17-dominant asthma." (PMID 39727954, 2024).
asthma (continued). "It has been reported that MBD2 is significantly increased in neutrophil-dominant asthma and positively regulates Th17 differentiation, while MINK1 negatively regulates Th17 cell differentiation, which has not been reported in Th17 dominant asthma." (PMID 36303542, 2022). "Next, to further understand the molecular mechanism of MBD2 involvement in Th17-dominant asthma, we attempted to determine whether there was any relationship between MBD2 levels and MINK1 expression in BECs exposed or not exposed to HDM + LPS." (PMID 36303542, 2022).
bipolar disorder (2 papers, 2022 to 2024). A disorder of the brain that causes unusual shifts in mood, energy, activity levels and the ability to carry out day-to-day tasks. "Searching the GWAS central for traits and diseases associated with MINK1, we found that MINK1 has been associated with partial epilepsy, as well as other NDD traits, including Bipolar disorder, Brain glutamate concentrations and Schizophrenia." (PMID 36012658, 2022).
congenital heart disease (2 papers, 2022 to 2024). A heart disease that is present at birth. "MINK1 contributes to the development of congenital heart disease and takes part in heart development, regulating Spemann organizer cell fate possibly via its role in the inhibition of canonical Wnt signaling and through HMGA2 protein." (PMID 39727954, 2024).
epilepsy (2 papers, 2022 to 2024). A brain disorder characterized by episodes of abnormally increased neuronal discharge resulting in transient episodes of sensory or motor neurological dysfunction, or psychic dysfunction. "Even though it is a single case, several layers of evidence from both induced patient neural cells as well as data mining of public databases indicate that the MINK1 disruptions are the likely explanation for autism, epilepsy and osteoporosis in the patient reported here." (PMID 36012658, 2022). "However, we suggest MINK1 as a novel candidate gene for autism, congenital cataract, epilepsy and osteoporosis." (PMID 36012658, 2022). "Considering that MINK1 has been implied to play a role in a variety of pathological conditions in humans, it would be beneficial to further test its influence in conditions present in the case of the patient: autism, congenital cataracts, epilepsy, and osteoporosis." (PMID 39727954, 2024).
glioblastoma (2 papers, 2023 to 2024). The most malignant astrocytic tumor (WHO grade IV). "MINK1 has been also implicated in the progression and prognosis of other malignancies, including glioblastoma (GBM), hepatocellular carcinoma (HCC), and head and neck squamous cell carcinoma (HNSC)." (PMID 39727954, 2024). "In addition, MINK1 downregulated IDH1, which is associated with bad prognosis in glioblastoma." (PMID 39727954, 2024).
Sepsis (2 papers, 2019 to 2024). Sepsis is defined as life-threatening organ dysfunction caused by a dysregulated host response to infection. "MINK1 knockdown has been reported to boost the survival rate and decrease the disease severity in LPS-induced sepsis and alum-induced peritonitis in mouse models, lowering the levels of IL-1β and IL-18 in serum of MINK1−/− mice compared to wild-type mice." (PMID 39727954, 2024). "Previous research has described an increased expression of synaptic genes during the progression from normal aging to neurodegenerative disease, including genes we observed to increase in older males on day 4 of sepsis (Cacnb1, Cacna1a, Ephb4, Glul, Jph3, Mink1, Nrxn2, Grasp)." (PMID 31278440, 2019). "MINK1 also takes part in NLRP3 inflammasome activation, which suggests its role in related diseases, such as type 2 diabetes, gout, and sepsis." (PMID 39727954, 2024).
Cerebral ischemia (1 paper, 2024). Restriction of arterial blood supply to the brain associated with insufficient oxygenation to support the metabolic requirements of the tissue. "Since miR-17-5p has been implicated in neuronal impairment in cerebral ischemia, its interactions with MINK1 could be explored in this context too." (PMID 39727954, 2024).
colorectal cancer (1 paper, 2024). A primary or metastatic malignant neoplasm that affects the colon or rectum. "Importantly, when MINK1 was depleted using siRNA, there was a significant reduction in the proliferation of colorectal cancer cells in which MINK1 regulation by APC was lost." (PMID 39727954, 2024). "Moreover, MINK1 was shown to interact with APC in colorectal cancer, which is an interesting direction for future investigations." (PMID 39727954, 2024). "MINK1 may take part in tumorigenesis via other signaling pathways as well, thus its function in colorectal cancer can be multi-dimensional." (PMID 39727954, 2024).
head and neck squamous cell carcinoma (1 paper, 2024). A squamous cell carcinoma that arises from any of the following anatomic sites: lip and oral cavity, nasal cavity, paranasal sinuses, pharynx, larynx, and salivary glands. "MINK1 expression was included in prognostic models for head and neck squamous cell carcinoma (HNSC) and hepatocellular carcinoma (HCC), being marked as a tumor suppressor gene for the former." (PMID 39727954, 2024).
hepatocellular carcinoma (1 paper, 2024). A malignant tumor that arises from hepatocytes. "MINK1, along with NF2, MYC, BIRC3, and CSNK1E, was also included in a prognostic model for hepatocellular carcinoma based on the expression of Hippo-related genes (HRGs) in adjacent tissues." (PMID 39727954, 2024).
orofacial cleft (1 paper, 2022). A disorder of facial skeleton that is characterized by cleft lip and/or cleft palate that result in feeding, speech and hearing problems caused by failures during development. "The protein-truncating DNMs were found in ACTL6A, ARHGAP10, MINK1, TMEM5 and TTN genes, all of which are loci with substantial annotation, functional and/or animal model data supporting their roles in orofacial clefts." (PMID 35817949, 2022).